PRSS30P (serine protease 30, pseudogene)
Synonyms: Disp; MGC5228; formerly TMPRSS8; TMPRSS8P
Gene: Transcribed unitary pseudogene on chromosome 16 (2,839,656 to 2,841,328, reverse strand). Ensembl gene ENSG00000172460.
Diseases named in the same sentence as PRSS30P in open-access papers:
PRSS30P is named in the same sentence as 2 diseases in open-access papers, as found by Europe PMC text mining. Sharing a sentence is not in itself a finding about the gene and the disease. The quoted sentences say what the papers report.
Sepsis (3 papers, 2021 to 2023). Sepsis is defined as life-threatening organ dysfunction caused by a dysregulated host response to infection. "Studies uncovered that the ribosome-related genes TLCD4, PRSS30P, and ZNF493 had a moderate performance to identify sepsis-induced acute respiratory distress syndrome (ARDS) in sepsis patients." (PMID 36299685, 2022). "Feature selection analysis revealed that three genes, TLCD4, PRSS30P, and ZNF493, showed moderate performance in identifying sepsis-induced ARDS from sepsis." (PMID 33818300, 2021). "We performed feature selection analysis and found that combination of three genes (TLCD4, PRSS30P, and ZNF493) and seven genes (TLCD4, PRSS30P, ZNF493, AGO2, SLC37A3, SLC2A1, and RPL11) showed moderate performance in identifying patients with sepsis and ARDS within 1 day after admission." (PMID 33818300, 2021).
PRSS30P also shares sentences with these, for which no sentence is quoted: acute respiratory distress syndrome (1 paper).